ASIC1 (acid sensing ion channel subunit 1)
Diseases named in the same sentence as ASIC1 in open-access papers (continued):
Sharing a sentence is not in itself a finding about the gene and the disease.
pancreatic cancer (continued). "Furthermore, the immunofluorescence assay demonstrated that ASIC1 and ASIC3 positively correlated with the expression of mesenchymal marker Vimentin, inversely correlated with epithelial marker E-cadherin in human pancreatic cancer samples." (PMID 28518134, 2017). "Inhibition of ASIC1 and ASIC3 with siRNA or pharmacological inhibitor significantly decreased [Ca2+]i and its downstream RhoA during acidity and, thus, suppressed acidity-induced epithelial–mesenchymal transition (EMT) of pancreatic cancer cells." (PMID 28518134, 2017). "In addition, ASIC1 and ASIC3 are positively correlated with expression of mesenchymal marker vimentin, but inversely correlated with epithelial marker E-cadherin in pancreatic cancer cells." (PMID 28518134, 2017). "As our previous results showed that the enhanced migration and invasion of pancreatic cancer cell in acidity were attributed to the acidity-induced EMT, we further investigated whether ASIC1 and ASIC3 contributed to the acidity-induced EMT." (PMID 28518134, 2017). "Reverse transcription-PCR (RT-PCR) and quantitative real-time RT-PCR (qRT-PCR) displayed that the mRNA of ASIC1 and ASIC3 in pancreatic cancer cell lines (PANC-1, SW1990, BxPC-3 and AsPC-1) significantly increased compared with normal pancreatic ductal cells (HPDE)." (PMID 28518134, 2017). "Immunohistochemical results showed that ASIC1 or ASIC3 were much more extensively expressed in pancreatic cancer tissues than that in paired adjacent noncancerous tissues." (PMID 28518134, 2017). "Therefore, ASIC1 and ASIC3 may represent exciting targets for therapeutic intervention in pancreatic cancer." (PMID 28518134, 2017). "In consistence with the results in pancreatic cancer cell lines, the immunofluorescence assay showed that ASIC1 and ASIC3 in pancreatic cancer specimens were increased compared with paired adjacent noncancerous tissues." (PMID 28518134, 2017). "Significantly, although without obvious effect on proliferation, knockdown of ASIC1 and ASIC3 in pancreatic cancer cells significantly suppresses liver and lung metastasis in xenograft model." (PMID 28518134, 2017). "ASIC1 and ASIC3 mRNA in pancreatic cancer tissues were significantly higher than that in paired noncancerous pancreatic tissues." (PMID 28518134, 2017).
Stroke (5 papers, 2018 to 2024). Sudden impairment of blood flow to a part of the brain due to occlusion or rupture of an artery to the brain. "Similarly, among miR-180 targets linked to stroke pathophysiology, the membrane channel acid sensing ionic channel, ASIC1, and the Na+/H+ exchanger should be mentioned." (PMID 34777204, 2021). "Similarly, among miR-180 targets linked to stroke pathophysiology, the membrane channel acid sensing ionic channel, ASIC1, and the Na+/H+ exchanger it should be mentioned." (PMID 34777204, 2021). "Due to its nanomolar potency for subtype ASIC1 and its inability (apart from stroke) to cross the blood–brain barrier (free form), DIZE is often limited to usage as a standard drug for in vitro modelling of new ASIC inhibitors." (PMID 37047556, 2023).
Anxiety (4 papers, 2018 to 2023). Intense feelings of nervousness, tension, or panic often arise in response to interpersonal stresses. "Both Grm8 and Asic1 are thought to play a role in modulating stress-related emotional traits such as fear and anxiety." (PMID 31164799, 2019).
colorectal cancer (3 papers, 2020 to 2024). A primary or metastatic malignant neoplasm that affects the colon or rectum. "In accordance with our findings, ASIC1 and ASIC2 are upregulated in colorectal cancer cells subjected to acidosis." (PMID 32764426, 2020).
diabetes (3 papers, 2015 to 2025). "At the FAIM2 locus on chr 12q13.12, we observed known genes associated with obesity, eating patterns, and diabetes-related traits, including ASIC1, AQP2, AQP5, AQP6, RACGAP1, and AC025154.2 (AQP5-AS1) along with FAIM2." (PMID 39813287, 2025).
ischemic stroke (3 papers, 2015 to 2023). A stroke disorder caused by obstruction of blood flow to the brain, due to thrombotic (local blood clot formation) or embolic (due to a blood clot or other material traveling from another site) event. "In addition, animals lacking ASIC channels (ASIC1-/-) show no obvious defects in physiological function, potentially providing hope for novel clinical therapies for both ischaemic stroke and the need to modify schizophrenia treatment regimens tailored to specific symptoms and patient subgroups." (PMID 36830777, 2023).
melanoma (3 papers, 2021 to 2022). A malignant, usually aggressive tumor composed of atypical, neoplastic melanocytes. "Even though in the literature there is little information about the expression of ASIC1 in melanomas and NMSC, the role in cancer progression has been proven in other tissues." (PMID 34199609, 2021). "Recently, we have proposed that the target of mambalgin-2 in melanoma cells could be the heteromeric acid-sensitive channels ASIC1/α-ENaC/γ-ENaC." (PMID 35837090, 2022). "As a result, ASIC1 expression in melanoma lesions is relatively elevated in comparison to other acid-sensitive channel subunits that may point on the possible ASIC1 participation in melanoma progression." (PMID 34680442, 2021). "Only ASIC1 and ASIC2 were shown to be expressed in human melanoma and skin cancer tissues previously." (PMID 34680442, 2021). "In this study, we investigate the expressions of ASIC1, ASIC2, TRPV1 and TRPV4 in squamous cell carcinoma (SCC), basal cell carcinoma (BCC), malignant melanoma (MM) and in nevus cell nevi (NCN)." (PMID 34199609, 2021). "In this study, we investigated the expression profiles of ASIC1, ASIC2, TRPV1 and TRPV4 in malignant melanoma (MM), squamous cell carcinoma (SCC), basal cell carcinoma (BCC) and in nevus cell nevi (NCN)." (PMID 34199609, 2021). "Recently, the ASIC1 expression was found in melanoma and non-melanocytic skin cancers, but the ASIC1 role in melanoma progression, as well as the possibility of ASIC1 targeting by selective inhibitors as a new therapeutic strategy for melanoma therapy were not investigated yet." (PMID 34680442, 2021).
multiple sclerosis (3 papers, 2015 to 2022). A progressive autoimmune disorder affecting the central nervous system resulting in demyelination. "In a murine model of multiple sclerosis, ASIC1 gene deletion or the administration of specific ASIC blockers reduced the progression of neurodegeneration." (PMID 26733809, 2015).
Obesity (3 papers, 2017 to 2025). Accumulation of substantial excess body fat. "In this case, rs1108923 is selected in the dataset because it maps to the upstream region of the obesity gene FAIM2, but the tool considers this variant to be within the region of ASIC1." (PMID 29163640, 2017). "ASIC1a in OPC reveals calcium permeability, however whether it has a role in leptin signaling needs to be determined; therefore, future studies would need to specifically focus on ASIC1 in OPC in order to confirm its relationship with obesity." (PMID 35207041, 2022). "It is remarkable to notice that ASIC1 is not in the list of the 12 obesity genes of the study selected." (PMID 29163640, 2017). "When OPC is destroyed or ASIC1 in OPC are not functioning properly, obesity risk is hypothesized to increase." (PMID 35207041, 2022).
atherosclerosis (2 papers, 2021 to 2024). A disease characterized by the build-up of fatty material and calcium deposition in the arterial wall resulting in partial or complete occlusion of the arterial lumen. "Targeting ASIC1 therapy represents a promising therapeutic approach for atherosclerosis." (PMID 39165945, 2024). "Taken together, this study reveals that ASIC1 is critical in linking extracellular acidification to cholesterol efflux and maybe a novel target for atherosclerosis therapy." (PMID 35126174, 2021). "At the same time, the acid-sensing ion channel 1 (ASIC1) of macrophages inhibits lipophagy in interaction with receptor-interacting protein 1 (RIP1), thereby promoting atherosclerosis formation." (PMID 39165945, 2024). "Thus, ASIC1 may be a novel therapeutic target for atherosclerosis." (PMID 35126174, 2021).
brain ischemia (2 papers, 2025). Diminished or absent blood supply to the brain caused by obstruction (thrombosis or embolism) of an artery resulting in neurologic damage. "Intriguingly, both ASIC1 and TREK-1 channels could contribute to promoting endothelial dysfunction upon strong and/or prolonged brain ischemia." (PMID 41488927, 2025).
intervertebral disc degeneration (2 papers, 2021 to 2022). "An up-regulation of ASIC1, ASIC2 and ASIC3 expression was described in the rodent and human nucleus pulposus in intervertebral disc degeneration." (PMID 36287977, 2022).
irritable bowel syndrome (2 papers, 2013 to 2025). Irritable bowel syndrome (IBS) is a chronic functional condition of the lower gastrointestinal (GI) tract characterized by abdominal pain or discomfort and disordered bowel habit (diarrhea, constipation, or fluctuation between the two). "Elevated ASIC1/3 expression has been observed in DRG neurons from patients with irritable bowel syndrome (IBS)." (PMID 40678181, 2025).
lung carcinoma (2 papers, 2021 to 2022). "Thus, its down-regulation in lung carcinoma samples may be linked with the up-regulation of ASIC1." (PMID 35837090, 2022). "Notably, the bioinformatic analysis only points on the ASIC1- and γ-ENaC-containing channels as on promising targets for lung cancer, but further study is required to confirmthe actual implication of these channels in lung carcinoma progression." (PMID 35837090, 2022). "However, the detailed molecular mechanisms of the ASIC1 oncogenic effects in lung adenocarcinoma as well as the prospects of the selective ASIC1 targeting for lung cancer therapy remain unclear." (PMID 35837090, 2022).
prostate carcinoma (2 papers, 2016 to 2021). A carcinoma that arises from epithelial cells of the prostate gland. "The clinical significance of ASIC1 is supported by the findings that ASIC1 is upregulated in a subset of prostate cancer cases." (PMID 27941930, 2016). "The present study provides evidence that ASIC1 plays a critical role in response to acidosis in prostate cancer." (PMID 27941930, 2016). "Finally, ASIC1 is upregulated in a subset of prostate cancer cases and ASIC1 knockout by CRISPR/Cas9 significantly suppresses cell invasion, and castration resistance both in vitro and in vivo." (PMID 27941930, 2016). "Moreover, ASIC1 promotes acidosis-induced expression of SNAI, that in turn leads to invasion of prostate cancer cells." (PMID 34680442, 2021).
pulmonary arterial hypertension (2 papers, 2018 to 2022). Pulmonary arterial hypertension (PAH) is a group of diseases characterized by mean pulmonary artery pressure >20 mmHg and elevated pulmonary arterial resistance leading to right heart failure. "Further research is necessary to determine the importance of this pH shift to activate ASIC1 in pulmonary hypertension." (PMID 36275633, 2022). "In the pulmonary circulation, ASIC1 is expressed in both PASMCs and PAECs and the goal of the current study was to determine if there is a differential contribution of EC and SM ASIC1 to the development of pulmonary hypertension." (PMID 36275633, 2022). "ASIC1 is expressed in both PASMCs and PAECs; however, the contribution of ASIC1a to the pathological mechanisms leading to pulmonary artery remodeling and the development of pulmonary hypertension in these two vascular cell types is unclear." (PMID 36275633, 2022). "We further demonstrate that deletion of SM-Asic1a in mice with established pulmonary hypertension effectively reversed increases in RVSP, RV hypertrophy, and vascular remodeling, signifying ASIC1 as a potential therapeutic target for pulmonary hypertension." (PMID 36275633, 2022). "Despite the requirement for ASIC1 in the development of pulmonary hypertension, this response is not dependent on an increase in total ASIC1 protein expression." (PMID 36275633, 2022). "Based on studies showing EC ASIC1 in mesenteric arteries contributes to endothelial-dependent vasodilation, we speculate PAEC ASIC1a may be protective against the development of pulmonary hypertension." (PMID 36275633, 2022).
skin cancer (2 papers, 2021). "We conducted immunohistochemistry using paraffin-embedded tissue samples from patients and found that most skin tumors express ASIC1/2 and TRPV1/4." (PMID 34199609, 2021). "In our study, we investigated the expressions of ASIC1, ASIC2, TRPV1 and TRPV4 in common skin tumors, namely SCC, BCC, NCN and MM." (PMID 34199609, 2021). "In conclusion, ASIC1, ASIC2, TRPV1 and TRPV4 are expressed by most common skin tumors." (PMID 34199609, 2021). "ASIC1, ASIC2, TRPV1 and TRPV4 in skin tumors might be involved in tumor progression, thus being potential diagnostic and therapeutic targets." (PMID 34199609, 2021).
acute disseminated encephalomyelitis (1 paper, 2022). Acute disseminated encephalomyelitis (ADEM) is a demyelinating disorder of the central nervous system. "Future research could concentrate on oligodendrocytic ASIC1 contribution to other demyelinating diseases, such as acute disseminated encephalomyelitis." (PMID 35207041, 2022).
Ataxia (1 paper, 2020). Ataxia refers to impaired coordination of voluntary muscle movement. "Other genes are related to cytoskeleton remodeling, including Cdh4, Pcdh9, Dock5, Dock3 for the proprioceptors (mutation of Dock3 is known to results in ataxia) and Stom and Pdlim1 for mechanoreceptors, as well as ion channels (Asic1 and Kcnip2 for proprioceptive fate)." (PMID 32826903, 2020).
Fabry disease (1 paper, 2025). Fabry disease (FD) is a progressive, inherited, multisystemic lysosomal storage disease characterized by specific neurological, cutaneous, renal, cardiovascular, cochleo-vestibular and cerebrovascular manifestations. "•ASIC1 and ASIC1a mRNA levels are upregulated in pain-related regions in a Fabry disease (FD) mouse model." (PMID 40686778, 2025). "In this study, we analyzed ASIC1 protein expression in a Fabry disease (FD) mouse model, examining both male and female animals at different ages (4 months vs. 8 months)." (PMID 40686778, 2025). "While elevated ASIC1 protein expression has been documented in various pain conditions, our study focuses on its involvement in the context of Fabry disease (FD)." (PMID 40686778, 2025).
gastroesophageal reflux disease (1 paper, 2022). A chronic disorder characterized by reflux of the gastric and/or duodenal contents into the distal esophagus. "Considering oesophageal heartburn pain associated with gastroesophageal reflux disease (GERD), ASIC1 and ASIC3 expression were recently found to be increased in biopsies of patients compared to healthy subjects, which positively correlates with symptom severity of heartburn and regurgitation." (PMID 36287977, 2022).
Lewis lung carcinoma (1 paper, 2022). "A similar situation is observed in Lewis cells: the parental Lewis lung carcinoma cells resistant to mambalgin-2 do not express ASIC1, while metastatic Lewis cells sensitive to mambalgin-2 express very high amounts of ASIC1." (PMID 35837090, 2022).
liver cancer (1 paper, 2025). An epithelial or non-epithelial malignant neoplasm that arises from the liver. "Acid-sensing ion channel 1 (ASIC1) is a key regulator of pH sensing, but its role in liver cancer progression and underlying mechanisms remain unclear." (PMID 40149892, 2025). "In conclusion, we have shown that the acidic tumor microenvironment enhances glycolysis and supports liver cancer cell survival by upregulating PFKM via the acid-sensing ion channel ASIC1." (PMID 40149892, 2025). "Our findings suggest that ASIC1 enhances liver cancer cell survival by upregulating PFKM-mediated glycolysis in an acidic tumor microenvironment." (PMID 40149892, 2025). "Taken together, our study shows that ASIC1 confers a survival advantage to liver cancer cells under acidic conditions by upregulating PFKM." (PMID 40149892, 2025). "We propose that targeting ASIC1 or PFKM could offer new therapeutic opportunities by depriving liver cancer cells of their metabolic adaptability to acidic environments." (PMID 40149892, 2025). "Under more extreme acidity (pH 6.0), ASIC1 expression was strongly induced in liver cancer cells, conferring a survival advantage that could be abrogated by ASIC1 knockdown." (PMID 40149892, 2025). "This ASIC1/PFKM axis is pivotal for adapting liver cancer cells to metabolic stress." (PMID 40149892, 2025). "In future research, we plan to investigate whether high ASIC1 expression in acidified liver tumors modulates immune cell infiltration or T-cell function, which may be highly relevant given the current focus on immunotherapy for advanced liver cancer." (PMID 40149892, 2025). "Our study reveals a link between ASIC1 and glycolytic metabolism in liver cancer, as PFKM expression was upregulated following ASIC1 overexpression." (PMID 40149892, 2025). "Western blotting assessed the expression of ASIC1 and glycolysis-related enzymes, with siRNA transfections used to investigate ASIC1 and phosphofructokinase muscle-type (PFKM) in liver cancer cell survival." (PMID 40149892, 2025).
lung adenocarcinoma (1 paper, 2022). A carcinoma that arises from the lung and is characterized by the presence of malignant glandular epithelial cells. "Bioinformatic analysis revealed a correlation between the increased expression of mRNAs coding the ASIC1 and γ-ENaC subunits with the worse survival prognosis for the patients with lung adenocarcinoma." (PMID 35837090, 2022). "Thus, both ASIC1 and γ-ENaC may be implicated in the lung adenocarcinoma progression." (PMID 35837090, 2022). "Bioinformatic analysis of the gene expression in the tissues from the patients with lung adenocarcinoma revealed possible implications of ASIC1, ASIC2, ASIC3, ASIC4, α-ENaC, and γ-ENaC in the disease progression." (PMID 35837090, 2022). "Finally, bioinformatics analysis showed that the increased expression of ASIC1 and γ-ENaC correlates with a worse survival prognosis for patients with lung adenocarcinoma." (PMID 35837090, 2022). "In line, the low expression of the gene coding ASIC1 and the high expression of the gene coding ASIC4 are correlated with better survival prognosis for the patients with lung adenocarcinoma at II–IV stages." (PMID 35837090, 2022).
malignant glioma (1 paper, 2021). A grade III or grade IV glioma arising from the central nervous system. "In malignant glioma ASIC1 plays a role in the growth and migration of the tumor cells." (PMID 34199609, 2021).
metastatic melanoma (1 paper, 2021). A melanoma that has spread from its primary site to another anatomic site. "Bioinformatic analysis confirmed up-regulation of the ASIC1 expression as a marker of poor survival prognosis for patients with metastatic melanoma." (PMID 34680442, 2021). "In addition, ASIC1 over-expression was found to be a marker of poor survival prognosis for the patients with metastatic melanoma." (PMID 34680442, 2021).
neuropathic pain (1 paper, 2025). Chronic pain caused by damage to nerve fibers. "Mambalgins are peptide inhibitors of acid-sensing ion channels type 1 (ASIC1) with potent analgesic effects in models of inflammatory and neuropathic pain." (PMID 40137874, 2025).
oral cancer (1 paper, 2023). "We also observed suggestive evidence of a positive relationship between ASIC1 expression and oral cancer, although this was not validated when using DBP GWAS as an instrument." (PMID 38089045, 2023).
pheochromocytoma (1 paper, 2025). "For example, ENaC alpha and ASIC1/2 were both found to be expressed in human pheochromocytoma wildtype cells and mutant cells with a knockdown of succinate dehydrogenase subunit B (SDHB), but there were significantly lower levels of the cleaved 60 kDa form of ENaC in SDHB KD cells." (PMID 41462875, 2025).